GSTA4 (glutathione S-transferase alpha 4)
Diseases named in the same sentence as GSTA4 in open-access papers (continued):
Sharing a sentence is not in itself a finding about the gene and the disease.
GSTA4 also shares sentences with these, for which no sentence is quoted: breast carcinoma (2 papers); colorectal (2); dysplasia (2); metabolic disorders (2); Parkinson disease (2); acute kidney injury (1); alcoholic liver diseases (1); alopecia (1); asthma (1); ciliopathies (1); coronary heart disease (1); deficiencies (1); diabetic cardiomyopathy (1); gastric cancer (1); hearing loss (1); hepatocellular carcinoma (1); kidney (1); liver diseases (1); liver fibrosis (1); malignant glioma (1); myeloma (1); Myocardial fibrosis (1); neuroblastoma (1); Neurodegeneration (1); Pleural effusion (1); rectal adenocarcinomas (1); respiratory syncytial virus infections (1); retinoblastoma (1).